APOE (apolipoprotein E)
Diseases named in the same sentence as APOE in open-access papers (continued):
Sharing a sentence is not in itself a finding about the gene and the disease.
cognitive decline (continued). "The most prominent and consistently associated genetic risk factor for AD and cognitive decline is the APOE (chromosome 19q13.2) ε4 allele." (PMID 34603005, 2021). "APOE ε4 allelic risk is associated with increased risk for sporadic AD and accelerated cognitive decline whereas, the ε2 and ε3 alleles are considered to have protective and neutral effects, respectively." (PMID 34603005, 2021). "In contrast, when the SAM index was considered with carrier status, greater SAM severity ratings were associated with cognitive decline only in participants carrying the APOE ε4 risk allele." (PMID 33692711, 2021). "A study on subjective cognitive decline showed that higher T3 levels were associated with better verbal memory performance (immediate and delayed recall tasks) in APOE ε4 carriers." (PMID 34103098, 2021). "We first analyzed the APOE ɛ4 and ɛ2 alleles given the body of literature relating these to AD and cognitive decline." (PMID 33757599, 2021). "In this study, we reported a significant association between APOE ε4 carriage and accelerated cognitive decline, consistent with the established literature." (PMID 34616288, 2021). "The association between APOE ε4 and cognitive decline in non‐demented individuals has been reported by several studies using comparable cognitive testing." (PMID 34041846, 2021). "A previous study using data from the Taiwan Longitudinal Study of Aging showed an association between the APOE genotype and the rate of cognitive decline in a predominantly Han Chinese population." (PMID 34214049, 2021). "It is well-known that ApoE gene polymorphism was associated with cognitive decline, which has been confirmed by some studies, mouse experiments, clinical studies and meta-analysis." (PMID 34135129, 2021). "APOE ε4 allelic risk has also been linked to steeper memory decline in normal aging and cognitive decline in MCI." (PMID 34603005, 2021). "The APOE ε4 allele is also differentially associated with cognitive decline in males and females, particularly having a more significant impact on females." (PMID 34610832, 2021). "APOE is a well-established AD risk factor with an important role in normal brain function and the APOE e4 allele has been associated with cognitive decline in PD." (PMID 33935957, 2021). "We depicted the associations between the ILAs and the OR of cognitive decline stratified by possession of an APOE ε4 allele." (PMID 34616288, 2021). "Recent data suggest that, first, greater Amerindian genetic ancestry is associated with protection against APOE ε4-related cognitive declines." (PMID 33716715, 2021). "According to some studies, the risk of future cognitive decline in aging individuals with olfactory loss depends on the ApoE gene; a plasma protein involved in lipid transport, and located on chromosome 19, carrying the three possible alleles ε2, ε3, and ε4." (PMID 34249327, 2021). "In the fully adjusted model, we observed a significantly higher odds of cognitive decline for individuals possessing APOE ε4 alleles (odds ratio, OR = 1.25, 95% CI: 1.03, 1.52; P = 0.026)." (PMID 34616288, 2021). "We also observed interactive effects of subtypes of leisure activities: participants who regularly engaged in productive activities were more likely to reduce the risk of APOE ε4-related cognitive decline." (PMID 34616288, 2021). "A prospective population-based cohort also showed that APOE ε4 genotype was associated with global cognitive decline." (PMID 34068064, 2021). "We wanted to ascertain the goodness of fit, map the standardised loadings back to the brain and then ask how these observed factors of brain change were associated with APOE status and cognitive declines." (PMID 33398085, 2021). "As such, the findings here support the notion that the TOMM40 ‘523’ poly-T repeat variants do play a role in modulating cognitive decline in PwP, independently of the effects of APOE ε4." (PMID 34234128, 2021).
cognitive decline (continued). "Our study also included other potentially confounding covariates, such as a measure of literacy, which was not accounted for in the models for most past studies that tested associations between APOE genotypes and cognitive decline." (PMID 34193248, 2021). "Few previous studies have examined the association between APOE genotype and cognitive decline over the adult life course as most studies are based on older adults who were followed for cognitive outcomes for less than 10 years." (PMID 33397450, 2021). "Subjective cognitive decline and neuropsychiatric symptoms are associated with brain structural alterations and APOE-4." (PMID 33920985, 2021). "Taken together, these results suggests that the effect of APOE on cognitive decline largely depends on Aβ status (while the polygenic risk for AD has some effects on cognition that are independent of Aβ pathology)." (PMID 34615922, 2021). "We have reported that ApoE proteins are critical determinants of brain phosphoinositol biphosphate (PIP2) homeostasis, and the ApoE4 isoform is dysfunctional in this process contributing to the increased susceptibility of cognitive decline in AD." (PMID 32632205, 2021). "In this paper, we applied Bayesian beta regression to assess the effect of APOE alleles on cognitive decline in a cohort of centenarians with longitudinal assessment of their cognitive function." (PMID 33488674, 2020). "Our study focused on the association between APOE alleles and cognitive decline in extreme old individuals." (PMID 33488674, 2020). "Despite some inconsistency, recent epidemiological genome-wide association studies have suggested that apolipoprotein E (ApoE) is a genetic vulnerability biomarker linked to cognitive decline in PD, as opposed to a risk factor for the etiology of PD." (PMID 33041748, 2020). "We found that a PRS-LOAD predicted rate of cognitive decline in a well-screened sample of healthy older adults who remained non-demented up until at least six years after last assessment, over and beyond the APOE ɛ4 allele." (PMID 32709845, 2020). "In conclusion, we examined the association between APOE alleles and cognitive decline in a cohort of centenarians." (PMID 33488674, 2020). "We investigated the relationship between urinary Alzheimer-associated neuronal thread protein (AD7c-NTP) levels and apolipoprotein epsilon 4 (ApoE ɛ4) alleles, as well as other factors that cause cognitive decline, in the cognitively normal population." (PMID 32587611, 2020). "Our results from this high-powered sample suggest that in elderly carriers of the ApoE-ε4 allele, odor identification impairment provides an indication of future cognitive decline, which has relevance for the prognosis of AD." (PMID 31760549, 2020). "The present findings confirmed that APOE ɛ 4 allele was associated with higher risk of cognitive decline." (PMID 32110803, 2020). "The hippocampal sparing type of AD is associated with a younger age at onset, lower frequency of the ApoE ε4 allele, greater tau burden particularly in the parietal cortex, faster cortical atrophy, and faster cognitive decline than the typical AD subtype." (PMID 33129364, 2020). "Previous studies have suggested that the association between APOE ɛ 4 and dementia is moderated by physical activity (PA), but the results remain inconclusive and longitudinal data on cognitive decline are missing." (PMID 32110803, 2020). "Using the Bayesian beta regression to analyze the association between APOE and cognitive decline among centenarians enrolled in the NECS is an important novelty of our analysis." (PMID 33488674, 2020). "The present study was designed to investigate the relationship between urinary AD7c-NTP levels and ApoE ɛ4 alleles, as well as with other factors associated with cognitive decline in the cognitively normal population." (PMID 32587611, 2020).
cognitive decline (continued). "Subjects carrying the APOE e4 allele had lower average FCSRT scores and, over time, subjects carrying the APOE e4 allele had lower FCSRT scores compared to non carriers i.e. APOE e4 carriers had a greater rate of cognitive decline as measured by the FCSRT-IR." (PMID 32108148, 2020). "Our findings provide the first fMRI evidence relating ApoE polymorphism to cognitive decline in PD, and they highlight the credibility of fMRI as a source of neuroimaging markers to explore the genetic basis of pathophysiology." (PMID 33041748, 2020). "The effect size of the association of p.P522R with the cognitive decline and pTau181 was similar to that of APOE-ε4, the strongest genetic risk factor for AD." (PMID 32166339, 2020). "We aimed to evaluate the interaction between ApoE ε4 status, Clock T3111C and Per2 C111G polymorphisms with cardiovascular profile in Subjective Cognitive Decline (SCD) and Mild Cognitive Impairment (MCI)." (PMID 32485802, 2020). "Carriers of the APOE e4 allele also had significantly higher rates of cognitive decline as measured by change in the FCSRT-IR." (PMID 32108148, 2020). "In stratified analysis by APOE ε4, the association between olfactory impairment and cognitive decline over time was present in both APOE ε4 carries (β = −0.07, 95% confidence interval [CI] −0.12 to −0.02) and ε4 noncarriers (β = −0.04, 95% CI −0.06 to −0.02)." (PMID 30651382, 2019). "Age (B = −0.07, SE = 0.01), APOE*4 carriage (B = −0.41, SE = 0.18), and diabetes (B = −0.18, SE = 0.10) were independently associated with faster cognitive decline (p < 0.05 for all)." (PMID 31335910, 2019). "We also found that in the APOE ε3 group, elevated BG was associated with cognitive decline in terms of immediate memory, executive function, and perceptual reasoning." (PMID 30984391, 2019). "Longitudinal studies have demonstrated that both memory complaints and APOE ε4 allele predict clinical cognitive decline in cognitively intact elderly individuals and additive effects were shown in individuals with both factors." (PMID 31159873, 2019). "(vi) In 100% of cases, the L/L genotype is exclusively associated with the APOE-4/4 genotype, and this haplotype (4/4-L/L) is probably responsible for early onset of the disease, a faster cognitive decline, and a poor response to different treatments." (PMID 30871086, 2019). "The other supporting evidence that lipid accumulation leads to a cognitive decline can be taken from the results obtained in the people having apolipoprotein E (ApoE) ε4 polymorphism." (PMID 31675964, 2019). "In the APOE ε3 group, elevated BG was associated with cognitive decline in immediate memory, executive function, and perceptual reasoning." (PMID 30984391, 2019). "Presence of an APOE-ε4 allele not only increases the risk of AD but also facilitates the rate of cognitive decline during the course of disease." (PMID 31831047, 2019). "APOE has three major isoforms (ɛ2, ɛ3, and ɛ4), with the ɛ4 increasing the risk of cognitive decline and AD in a dose-dependent fashion." (PMID 31221191, 2019). "This study confirmed the association between APOE genotype and the rate of cognitive decline in a predominantly Han Chinese population." (PMID 30339707, 2018). "In a subsequent analysis, CSF ferritin was associated with cognitive decline in cognitively normal subjects, but the association was strongest in APOE ε4 carriers." (PMID 30488277, 2018). "In multivariate analyses, possession of the APOE e4 allele is one of the few robust independent predictors of relatively greater older-age cognitive decline." (PMID 29546429, 2018). "We have previously reported that while an AD risk weighted PRS was associated with cognitive decline, the association was only observed in carriers of the apolipoprotein E (APOE) ε4 allele." (PMID 30620773, 2018).
cognitive decline (continued). "Although the gene-dose effect of ApoE ε4 allele on the risk of both cognitive decline and AD has been indicated by previous studies, to date, the ApoE ε4 allele is solely suggested as a risk factor for AD rather than its cause." (PMID 29559956, 2018). "This study confirmed the association between APOE genotype and cognitive decline in a predominantly Han Chinese population of older adults." (PMID 30339707, 2018). "We confirmed the relationship found in studies of European-ancestry individuals that a risky APOE genotype was associated with steeper age-related cognitive decline in this population of Taiwanese older adults primarily of Chinese Han ancestry." (PMID 30339707, 2018). "The AD genetic risk scores, including and excluding APOE effects, were strongly associated with cognitive decline in all domains (min Puncor = 3.2 × 10− 29)." (PMID 30041668, 2018). "For example, source EEG functional network disruption in AD and MCI is associated with cognitive decline and APOE genotype." (PMID 28243198, 2017). "The genes selected for investigation included genetic polymorphisms with well-described influences on cognitive function, brain plasticity, and risk of ageing-related cognitive decline (APOE, BDNF Val66Met, KIBRA, COMT Val158Met, SERT 5-HTTLPR)." (PMID 30631459, 2017). "More recently, ApoE gene polymorphism has been implicated with cognitive decline in healthy individuals." (PMID 28824412, 2017). "In a collaborative cohort study, Darren Lipnicki and colleagues investigate associations between age-related cognitive decline and sex, education, and apolipoprotein E genotype across ethnocultural groups and geographic regions." (PMID 28323832, 2017). "With such a diverse overall sample, our study should also help to clarify how sex, education, and APOE*4 carrier status are associated with cognitive decline." (PMID 28323832, 2017). "Olfactory dysfunction (tested by CC-SIT) in the presence of one or more APOE-ε4 alleles was related to a 4.9 times the risk of cognitive decline in the longitudinal study of memory and aging in the Japanese-American community in King County." (PMID 27765032, 2016). "ApoE genotype is a well-described genetic risk factor for AD associated with early deficits in episodic recall, higher rates of cognitive decline before the diagnosis of MCI or AD, and age-related memory decline earlier in life." (PMID 26868820, 2016). "On the other hand, APOE ε4 is associated not only with AD but also with cognitive decline, depressive symptoms, stroke, hypertension, coronary heart disease, cardiovascular disease, and diabetes." (PMID 27168072, 2016). "The possibility of an antagonistic pleiotropy has been suggested, whereby possession of APOE ɛ4 alleles confers cognitive advantage in younger participants though this reverts to cognitive decline with advancing age." (PMID 27395443, 2016). "Several studies suggested the APOE ε4 genotype to be associated with a faster cognitive decline and clinical progression of AD, whereas other studies doubt accelerated deterioration in APOE ε4 carriers." (PMID 27410431, 2016). "Several reports demonstrated that APOE ε4 is associated with AD, cognitive decline, depressive symptoms, stroke, hypertension, coronary heart disease, cardiovascular, and diabetes." (PMID 27168072, 2016). "The current results support a vascular-focused theory of AD risk, which posits that cerebrovascular damage contributes to cognitive decline and suggests that ApoE genotype modifies the association between CBF and verbal memory in normal aging." (PMID 27445794, 2016). "The independent association between the poor OI and cognitive decline were explored, after adjusting the possible confounders including APOE genotype." (PMID 27765032, 2016).
cognitive decline (continued). "This person, who is homozygous for the ApoE ε4 allele, demonstrated both subjective and objective evidence of cognitive decline, with preserved activities of daily living, and thus would fit best with a diagnosis of mild cognitive impairment." (PMID 27294343, 2016). "Future studies are needed to clarify if differences in DHA transport in participants carrying the APOE ε4 allele appear earlier in life, before the onset of cognitive decline." (PMID 27358067, 2016). "Here we have shown in a sample of White participants from the HRS, that cognitive decline among individuals with one or more APOE ε4 alleles in addition to AD risk genes of small effect are greater than the risk associated with APOE ε4 alone." (PMID 26102276, 2015). "Individuals with multiple AD risk genes in addition to having one or more APOE ε4 alleles are at greater risk of cognitive decline than individuals with either APOE ε4 or a high genetic risk score." (PMID 26102276, 2015). "Given the current findings and their consistency with previous data gathered over longer time intervals it is possible that the Aβ related cognitive decline reported in CN older adults is being driven also by the additive effects of the APOE ε4 allele." (PMID 26430784, 2015). "In studies from China, APOE ε4 has been correlated with AD risk, as well as cognitive decline and memory performance in mild cognitive impairment (MCI)." (PMID 25738563, 2015). "The APOE-ε4 allele not only is considered a risk factor for AD, but is now also being used as a predictor for cognitive decline." (PMID 25859282, 2015). "In this study of 7,451 participants from the HRS, individuals with one or more APOE ε4 alleles and a high g-score appear to experience greater cognitive decline over time than individuals with either APOE ε4 or a high g-score alone." (PMID 26102276, 2015). "The APOE ε4 allele is considered to be one of the major genetic risk factors for AD and has been associated with cognitive decline in neuropsychological studies." (PMID 24914687, 2014). "Presence of the apoE ε2 allele was reported to have an association with improvement in episodic memory over time and to reduce the risk of cognitive decline among older adults." (PMID 25161798, 2014). "The APOE genotype is besides one of the most important genetic risk factors for cognitive decline, consistently shown to be associated with survival and longevity." (PMID 23483953, 2013). "Physical activity, on the other hand, significantly reduced the probability of future cognitive decline, but only in APOE-ε4 allele carriers." (PMID 24961307, 2013). "Apolipoprotein-ε4 (APOE-ε4) is a major genetic risk factor for AD, preclinical cognitive decline and early mortality." (PMID 23418430, 2013). "In two studies, greater effects of PA on cognition or future incidence of cognitive decline have been observed in those who carry at least one copy of the APOE-ε4 allele." (PMID 24961307, 2013). "A meta-analysis of data of 34 previously published studies showed that education, hypertension, objective indices of health, cardiovascular disease, and apolipoprotein E (APOE) were associated with cognitive decline in old-age subjects." (PMID 23139907, 2012). "The main objective of the current study was to provide a comprehensive assessment of the potential of n-3 LC PUFAs to slow cognitive decline in normal elderly people, and included ApoE-ε4 allele carriage as a potential moderating factor." (PMID 22011460, 2011). "A number of genetic risk factors for AD have been proposed, however only the apolipoprotein E (APOE) ε4-allele, which lowers the age of onset and accelerates the cognitive decline, has a large effect." (PMID 22216330, 2011). "Cognitive decline was significantly associated with more severe disability, higher vascular risk scores and the presence of the APOE e4 allele." (PMID 20046406, 2008).